ESR1 (estrogen receptor 1)
Diseases named in the same sentence as ESR1 in open-access papers (continued):
Sharing a sentence is not in itself a finding about the gene and the disease.
breast cancer (continued). "The input features are the corresponding genes of well-established breast cancer biomarkers (ESR1, PGR, ERBB2, MKI67, PLAU) and the hybrid ensemble approach's final selected genes." (PMID 34290286, 2021). "Breast cancer is subtyped by the expression levels of the estrogen receptor (ER, the gene of which is named ESR1), progesterone receptor (PR), and human epidermal growth factor receptor (HER)-2." (PMID 34359286, 2021). "We used GSVA analysis as well and noticed that C5AR2 was significantly associated with metastasis as well as relapse of breast cancer and the upregulation of ESR1, a proven oncogene in breast cancer involved in endocrine resistance." (PMID 34595119, 2021). "The top ranked putative regulator in luminal breast invasive carcinoma (BRCA luminal) was ESR1, which has been previously shown as a predictive biomarker of breast cancer." (PMID 33778495, 2021). "This was confirmed by identifying ESR1 as the most frequent breast cancer cell-related factor binding to the CDH1 promoter sequence using the DB cistrome toolkit." (PMID 33420368, 2021). "Given the heterogeneous nature of breast cancers, we sought to further investigate the regulation of ESR1 by menin and assess the putative relationship between ESR1 dysregulation due to menin inactivation and the occurrence of human breast cancer subtypes." (PMID 34561764, 2021). "Another recent study reported that LINC01116 was upregulate in breast cancer and reduced the effects of overexpressing miR-145 on the expression of ESR1 to promote cancer progression." (PMID 33535997, 2021). "For example, myogenic differentiation 1 (MYOD1) induces more than 16,000 eRNAs during myogenic differentiation, while estrogen receptor 1 (ESR1) induces thousands of eRNAs to maintain transcriptional circuitry in breast cancer." (PMID 33119754, 2021). "Although the efficacy of combining HT and CDK4 and CDK6 inhibitor in patients with ESR1+/HER2− breast cancer, the promising benefit of CDK4 and CDK6 drug inhibitors in other neoplasms has not been extensively tested." (PMID 34445095, 2021). "We find that, by analyzing genetic variations of TF-DNA bindings, the interaction of FOXA1 with co-factors such as ESR1 and E2F1, and the interaction of TFs with chromatin features (i.e., enhancers) play a key role in breast cancer susceptibility." (PMID 34518541, 2021). "For example, the gene coding for the estrogen receptor, ESR1, is often found to be mutated in metastatic ER+ breast cancers previously treated with estrogen therapy." (PMID 34075047, 2021). "Variation of PvuII in the ESR1 gene is related to OS in postmenopausal, early HR + breast cancer patients treated with exemestane in the TEAM study." (PMID 33547330, 2021). "In this study, we investigated ESR1 PvuII as a prognostic and predictive factor for the selection of therapy in advanced breast cancer." (PMID 34930150, 2021). "In contrast, in ctDNA sequencing MAPK alterations were more common in patients with ESR1 mutations overall (p = 0.001), and in HR + HER2- breast cancer (p = 0.02)." (PMID 33893289, 2021). "Similar to SALL2, SALL1 is downregulated in human breast cancer cells and tissues and correlates with ESR1 expression." (PMID 34944911, 2021). "The ESR1 gene suffers methylation changes in many types of cancers, including breast cancer (BC), the most frequently diagnosed cancer in women that is also present in men." (PMID 34863151, 2021).
breast cancer (continued). "The mRNA expression level of DNAJC12 is generally higher in breast carcinoma, especially in ESR1-positive breast carcinoma tissues." (PMID 33718139, 2021). "All signs point to the conclusion that ESR1 acts upstream of DNAJC12 to enhance DNAJC12 expression in breast carcinoma." (PMID 33718139, 2021). "In breast carcinoma, ESR1 was positively correlated with DNAJC12 and ERBB4, and DNAJC12 was positively correlated with ERBB4." (PMID 33718139, 2021). "Associations were also observed for the cistromes of established breast cancer transcription factors (TFs); ESR1, FOXA1, and GATA3." (PMID 31910858, 2020). "In breast cancers, correlations between ESR1 gene status and estrogen receptor protein levels were measured by ligand binding assay (LBA) and immunohistochemistry." (PMID 32774370, 2020). "Knockdown of FOXP1 decreased gene expression of Gata3 and Esr1, along with diminishing ERα protein expression in WT mouse mammary epithelial cells as well as in human breast cancer cells, MCF7." (PMID 32934200, 2020). "Genome-wide association studies have revealed that multiple single-nucleotide polymorphisms in the intergenic region between estrogen receptor 1 and coiled-coil domain containing 170 (CCDC170) are associated with breast cancer risk." (PMID 33291081, 2020). "Estrogen receptor, a protein encoded by the ESR1 gene, is expressed in the majority of breast cancers and is one of the key factors for disease classification and treatment definition." (PMID 32309212, 2020). "For instance, FOXA1 and ESR1 (also known as ERα) are part of a transcriptional network responsible of the control of gene expression patterns of luminal A breast cancer." (PMID 32850701, 2020). "In the present study, analysis of three genomic profiles from the GEO indicated that FABP7 and ESR1 were essential indicators of response to anthracycline and taxanes in breast cancer." (PMID 33292226, 2020). "Genome-wide association studies have revealed that single-nucleotide polymorphisms residing in the intergenic region between estrogen receptor 1 (ESR1) and coiled-coil domain containing 170 (CCDC170) at 6q25.1 are associated with breast cancer risk." (PMID 33291081, 2020). "Depletion of AFF4 by CRISPR-Cas9 reduced the recruitment of transcriptional elongation factors and RNA polymerase II to the ESR1 transcription start sites, decreased ESR1 gene expression, and inhibited the growth of ER-positive breast cancer cells." (PMID 32265480, 2020). "CDK7 inhibition inhibits the growth of ESR1-mutant breast cancer and can overcome chemotherapy resistance in breast cancer." (PMID 31530935, 2020). "RSPO1 upregulates the expression of Esr1 and ERα signaling targets Pgr and Greb1 (growth regulation by estrogen in breast cancer 1) in a dose-depending manner." (PMID 32749219, 2020). "Eleanors are clusters of ncRNAs that accumulate around the estrogen receptor-α (ESR1) gene locus in long-term estrogen deprivation (LTED) breast cancer cells, and markedly enhance the transcription of the ESR1 gene." (PMID 32047236, 2020). "The estrogen hormone receptor ESR1 is a nuclear hormone receptor that is expressed in approximately 70% of patients with breast cancer." (PMID 33324444, 2020). "By analyzing multiple large patient cohorts with transcriptomes, we found that estrogen response early scores only moderately correlated with the expression of ESR1 in the whole breast cancer cohort." (PMID 33260779, 2020). "XBP1s is a transcription factor that can induce the expression of ESR1, and these two genes are co-expressed in breast cancer tissues." (PMID 33291081, 2020). "Previously, we reported a recurrent ESR1 fusion called ESR1-CCDC170 in 6–8% of the luminal B breast cancers that has a worse clinical outcome after endocrine therapy." (PMID 32771039, 2020). "ESR1 was significantly upregulated in the 4 luminal A breast cancer samples compared with that in the 4 luminal B breast cancer samples." (PMID 32500028, 2020).
breast cancer (continued). "The aggressiveness of breast cancer is associated with high promoter methylation of TWIST, SFRP1, ESR1, P16, and APC in lymph node positive breast cancer cases." (PMID 32183060, 2020). "Two differentially expressed genes, including FABP7 and ESR1, were identified to be potential indicators of response to anthracycline and taxanes for breast cancer." (PMID 33292226, 2020). "Conversely, NCS‐1 expression is negatively correlated to FOXA1, ESR1, and PGR, which are more commonly associated with the breast cancer luminal subtype." (PMID 31647602, 2020). "In breast cancer samples, overexpression of ESR1 can promote cell growth by enhancing the IGF signaling pathway." (PMID 32722439, 2020). "The results showed that the abnormal expression of 4 hub genes (PTGS2, ESR1, FOS, and NOS3) was associated with unfavorable overall survival of breast cancer patients." (PMID 33149754, 2020). "For example, neddylation inactivation by the specific inhibitor MLN4924 can prevent FOXO3 nuclear export, decrease its binding to the ESR1 (oestrogen receptor) gene promoter and improve fulvestrant sensitivity in breast cancer." (PMID 32372224, 2020). "Nonetheless, MSI2 was also reported to act as an upstream regulator of ESR1, leading to luminal breast cancer proliferation and invasion, whereas MSI2 overexpression was associated with a better prognosis in breast cancer." (PMID 32448269, 2020). "Intriguingly, ESR1 expression was positively linked to hsa-let-7a-5p, hsa-let-7c-5p, hsa-miR-30a-5p, hsa-miR-29c-3p, hsa-miR-10b-5p, hsa-miR-195-5p, and hsa-miR-497-5p in ERα positive breast cancer." (PMID 32500028, 2020). "Experimental validation showed that these miRNAs were significantly downregulated after knockdown of ESR1 in ERα positive breast cancer cells." (PMID 32500028, 2020). "The purpose of the current study was to determine the ESR1-mediated miRNA-mRNA regulatory network in ERα positive breast cancer." (PMID 32500028, 2020). "Intriguingly, FOXM1 was predicted to regulate cell type-specific genes including ESR1 in the ER+ breast cancer cell line MCF-7 by directly binding to cis-regulatory elements that include the canonical FKH motif." (PMID 32858881, 2020). "The central node is ESR1, which has been the focus of breast cancer research for some time and also has clinical implications in endometrial, ovarian, and other types of cancers." (PMID 33102593, 2020). "Intriguingly, ESR1 expression was positively correlated with miRNA expression, miRNA expression was negatively correlated with mRNA expression, and ESR1 expression was negatively correlated with mRNA expression in ERα positive breast cancer." (PMID 32500028, 2020). "In an ESR1-luciferase reporter assay using T47D (a human breast cancer cell line), LGR4 knockdown also inhibited the luciferase activities induced by RSPO1." (PMID 32749219, 2020). "MSI2 directly regulates estrogen receptor by binding to ESR1 resulting in breast cancer cell growth." (PMID 32139710, 2020). "For example, MSI2 influenced breast cancer cell growth by binding to specific sites in ESR1 RNA and by increasing ESR1 protein stability." (PMID 33229623, 2020). "In this context, most studies focus on breast cancer, where AP-2 responsive elements were found in the estrogen receptor gene (ESR1) and the cERBB2 gene (HER2/neu)." (PMID 32143573, 2020). "For both ESR1 and RAD51B our decorrelation approach was the only one that concluded a statistically significant association between SNP-set in those genes with breast cancer." (PMID 32287273, 2020).
breast cancer (continued). "According to a recently published meta-analysis, ESR1 promoter methylation is related to a worse overall survival of patients with breast cancer." (PMID 33233830, 2020). "In this study, we successfully established a comprehensive ESR1-regulated miRNA-mRNA regulatory system in ERα positive breast cancer by combination of a series of in silico analyses and experimental validation." (PMID 32500028, 2020). "Among breast cancers classified as ER-negative ones, a large fraction exhibited ESR1 deletion (55%)." (PMID 32774370, 2020). "The method reveals that ESR1, FGFR2, VDR, CNTNAP2, and BRCA2 have a weak association with sporadic breast cancer in the Uruguayan population." (PMID 33126731, 2020). "The search strategy terms for these systematic review and meta-analyses were as follows: (‘estrogen receptor alpha’ OR ‘ESR1’) AND (‘breast neoplasms’ OR ‘breast cancer’) AND (‘neoplasm metastasis’ OR ‘metastasis’ OR ‘resistance’)." (PMID 33233830, 2020). "In breast cancer, ESR1 methylation can be used as a prognostic and predictive biomarker with diagnostic utility." (PMID 33198064, 2020). "Among them, FOXA1 and ESR1 form part of a transcriptional network responsible of the control of gene expression patterns in luminal A breast cancer, the most common breast cancer subtype." (PMID 32850701, 2020). "CCDC170 was found to be co-expressed with ESR1 in breast cancer tissues, and an ESR1-CCDC170 rearrangement was discovered in luminal B breast tumors." (PMID 33291081, 2020). "In vitro studies showed that Per2 suppresses Esr1 transcription and induces Esr1 degradation and that Per2 is estrogen-inducible in Esr1 positive breast cancer cells." (PMID 32625167, 2020). "The Eleanor cluster of non-coding RNAs is localised upstream of estrogen receptor-α (ESR1) gene locus in estrogen-deprived breast cancer cells." (PMID 32047236, 2020). "The relationship between ESR1-miRNA, miRNA-mRNA, or ESR1-mRNA pairs was validated in clinical ERα positive breast cancer." (PMID 32500028, 2020). "ESR1, a nuclear hormone receptor and oncoprotein, is expressed in approximately 70% of breast cancers." (PMID 32368784, 2020). "RET is a transcriptional target of estrogen receptor alpha (ESR1) and several studies have reported its overexpression, particularly in ER+ breast cancer as well as its association with endocrine resistance." (PMID 32326537, 2020). "Herein, we build on evidence for breast cancer bimodality by showing bimodal age-at-incidence across categories of immunohistochemistry-based ER expression, ESR1 levels, as well as PAM50 intrinsic subtype." (PMID 31535320, 2020). "Binding with estrogen, ESR1 is not only essential for sexual development, reproductive function, and bone formation but is also involved in pathologic processes, including breast cancer, endometrial cancer, and osteoporosis." (PMID 32921307, 2020). "On the contrary, ESR1 mRNA level was 4.032-fold (p = 3.37E−9) increased in breast cancer samples compared with normal tissue samples in Curtis breast statistics." (PMID 33292226, 2020). "The outlier analysis identified HER2 as overexpressed in 33 breast cancer data sets and ESR1 as overexpressed in 3 breast cancer data sets whereas BRF2 is overexpressed in 8 breast cancer data sets." (PMID 33176745, 2020). "Depletion of AFF4 by siRNA or CRISPR/Cas9 dramatically reduces expression of ESR1 and its target genes, consequently inhibiting breast cancer cell growth." (PMID 32265480, 2020).
breast cancer (continued). "For instance, genome-wide association studies performed by the Breast Cancer Association Consortium showed that BRCA2, CHEK2, ESR1, FGFR2, MDM4 and PIK3R3 carry germline variants associated with BC development." (PMID 32210335, 2020). "This study aims to assess the influence of SNPs in ESR1 gene (rs397512133, rs397510462, rs851327560, rs397510612, rs852887655, rs852684753 and rs852398698) in canine mammary tumors characteristics and progression." (PMID 31506083, 2019). "DACH1 expression is dysregulated in human breast cancer and acts as an endogenous inhibitor of ESR1 function." (PMID 32117782, 2019). "Exogenous expression of ∆DCCDC170 in ER+ breast cancer cells led to enhanced growth and reduced sensitivity to tamoxifen suggesting a role for ESR1-e2>CCDC170 in endocrine therapy resistance." (PMID 31106278, 2019). "A similar downregulation of ESR1 protein level by miR-221 and -222 was observed in T47D luminal A type breast cancer cells, whereas ESR1 expression is undetectable in the HER2+ subtype SKBr-3 cells." (PMID 30833639, 2019). "c-MYB is overexpressed or mutated in a variety of cancers, including breast cancer, where its expression generally correlates with that of ESR119 because ESR1 signaling positively regulates MYB expression." (PMID 30833639, 2019). "Additional studies on ESR1 fusions will further support the causal role ESR1 fusions and have significant diagnostic and clinical implications since pathogenic ESR1 fusions could be used as biomarkers to stratify patients for individualized healthcare in ER+ breast cancer." (PMID 31106278, 2019). "ESR1 is also represented in this axis and is known to interact with NF-κB transcription factors in order to influence progression of breast cancer to advanced stage and metastatic disease." (PMID 31136639, 2019). "More recently, a study reported a breast cancer patient harboring an ESR1 amplification showed tumor regression in a liver metastasis after receiving estradiol treatment as a primary therapy." (PMID 31106278, 2019). "In a previous study by our group, FISH analysis revealed that the estrogen receptor 1- gene (ESR1) was amplified in 15.5% of breast cancers." (PMID 31396514, 2019). "The ABC-BIO study recruits patients at the Royal Marsden Hospital with advanced breast cancer with accessible metastatic deposits for DNA sequencing using the Breast NGS v1.1 probe set including probes to capture ESR1." (PMID 30563991, 2019). "Considered the pathophysiologic functions of CYP19A1 and ESR1/ESR2-mediated signaling pathway in breast cancer seem as more complicated than what we have already known, more precise evaluation will be needed in urgent." (PMID 31741086, 2019). "The basal-like breast tumor subtype largely overlaps the triple negative type of breast cancer, which lacks or shows a low level of ESR1 and PGR expressions, and lacks ERBB2 amplification." (PMID 30621577, 2019). "Evaluation of SNPs from 3,677 women with TNBC and 4,708 controls supported the association of 25 known breast cancer susceptibility loci, including 2q35, LGR6, MDM4, TERT, ESR1, TOX3, and 19p13.1 with TNBC." (PMID 31379942, 2019). "Although less well studied, there are indications that glucocorticoid receptors enhance the ESR1-dependent induction of KDM4B in breast cancer." (PMID 30759871, 2019). "Essential genes associated with essential binding sites include estrogen receptor 1 (ESR1), the master transcription factor for ER+ breast cancer cells, and TRPS1, another transcription factor that is known to be associated with ER+ breast cancer progression." (PMID 31727847, 2019). "This study confirmed previous associations between increased breast cancer risk and SNPs in CASP8, TOX3 and ESR1." (PMID 31125336, 2019).